ENSG00000283761 (novel protein)
Gene: Protein-coding gene on chromosome 1 (99,970,011 to 100,083,321, forward strand). Ensembl gene ENSG00000283761.
Genetic constraint (gnomAD): Loss-of-function variants: 23 observed, 41.24 expected, observed/expected ratio (o/e) 0.56, 90% interval 0.4 to 0.79. Missense variants: 340 observed, 510.87 expected, observed/expected ratio (o/e) 0.67, 90% interval 0.61 to 0.73. Synonymous variants: 173 observed, 189.94 expected, observed/expected ratio (o/e) 0.91, 90% interval 0.8 to 1.03.